STAT3 (signal transducer and activator of transcription 3)
Diseases named in the same sentence as STAT3 in open-access papers (continued):
Sharing a sentence is not in itself a finding about the gene and the disease.
cancer (continued). "Moreover, STAT3 knockdown or overexpression of S727A point-mutated STAT3, an inactive form, increased apoptosis in TICs, while overexpression of S727E point-mutated STAT3, an active form, decreased apoptosis in bulk cancer cells." (PMID 27306323, 2016). "Constitutive STAT3 activation has been linked to the development of various cancer types." (PMID 26911838, 2016). "Many cancers, including those associated with members of the gammaherpesvirus family, Kaposi’s sarcoma-associated herpesvirus and Epstein-Barr virus, express elevated levels of active host signal transducer and activator of transcription-3 (STAT3)." (PMID 27486189, 2016). "Abnormal STAT3 signaling has also been associated with promoting cellular proliferation, weakening the immune system, and promoting angiogenesis and inflammation in cancer." (PMID 27148537, 2016). "Indeed, cytotoxic reagent CDDP not only enrich HNSCC CSCs by debulking proliferating cancer cell but also increase the fraction of stem cell by inducing putative self-renewal marker Bmi1 and associated with STAT3 activation." (PMID 26556875, 2015). "One reason may be the positive association between YB-1 and the levels of activated STAT3, which is a pro-survival factor in several cancer cells." (PMID 26512918, 2015). "HIF1, NFkB, JNK, STAT3 and TGFβ activation in the stroma occurs with increased catabolism, which in turn can promote cancer proliferation and can cause immunosuppression and angiogenesis, making cancer more invasive." (PMID 25915429, 2015). "The cancer-causing propensity of constitutively activated STAT3 protein and the evidence of potential clinical benefits of blocking constitutive STAT3 signaling make strong arguments for target validity of STAT3 for drug intervention in cancer therapy." (PMID 26464811, 2015). "Since cancer is associated with aberrant gene expression patterns, increasing attention has been focused on transcription factors like signal transducer and activator of transcription 3 (STAT3) which lies at the convergence points of many oncogenic signaling pathways." (PMID 26000098, 2015). "Furthermore, the anti-cancer activity of FSREE was associated with a decreased level of phosphorylated Janus kinase/signal transducer and activator of transcription 3 and extracellular-signal-regulated kinase signaling activity." (PMID 25373392, 2015). "Indeed, phosphorylated STAT3 (p-STAT3) was not only abundant in the nuclei of PCCs and cancer-associated fibroblasts (CAFs) in KRC tumors, but was also frequently present in ECs, identified using a murine-specific VE-Cadherin antibody." (PMID 25762644, 2015). "Several studies independently support the hypothesis of regulatory circuits between miR and STAT3 pathway in different cancer contexts linked to inflammation as a key component favoring tumorigenesis." (PMID 26116514, 2015). "In addition to Erk1/2 signaling, other studies have shown that the expression of MMP-2/9 is also regulated by the STAT3 pathway, and activation of STAT3 is also associated with drug resistance of cancer cells." (PMID 26501276, 2015). "Stat3 activation is linked to the development of doxorubicin resistance in cancer cell lines." (PMID 26169986, 2015). "Elevated STAT3 activation is associated with MDSCs and poor survival in cancer patients." (PMID 28781374, 2015). "Importantly, STAT3 is prominently activated at sites of chronic inflammation by IL-6 and initiates a positive that is highly predisposing condition for cancer." (PMID 25238263, 2014).
cancer (continued). "Key inflammatory pathways, such as the NF-κB, AP-1 and STAT3 pathways, are implicated in the proliferation, transformation, survival, invasion, angiogenesis, metastasis, chemoresistance and radioresistance of cancer." (PMID 24621579, 2014). "Several proteins have also been implicated in regulating the function of STAT3 in cancer cells." (PMID 24995504, 2014). "Moreover, induction of anoikis resistance by STAT3 was also associated with enhanced cell migration and invasion of cancer cells in vitro and high metastatic potential in vivo." (PMID 25216522, 2014). "Therapeutic targeting of STAT3 has been shown to revert cancer-associated immune suppression." (PMID 24657910, 2014). "On activation, Stat3 molecules are translocated to nucleus, where they activate transcription of a series of target genes including c-Myc, survivin, and cyclin D1 that are closely associated with the growth, survival, and progression of cancer cells." (PMID 25063218, 2014). "Furthermore, reduced expression of SOCS3 has been observed in various human cancers and is associated with constitutive STAT3 activation." (PMID 24757565, 2014). "Furthermore, many in vivo and in vitro assays have demonstrated the association of STAT3 activation with the development and maintenance of several cancer types." (PMID 25417721, 2014). "More recently, STAT3 has been implicated in the self-renewal of cancer stem cells." (PMID 24995504, 2014). "The microRNA upregulated by STAT3 activation might be associated with the mechanisms of cancer invasion, migration and resistance to anti-cancer agents including cytotoxic or targeted therapies." (PMID 24675568, 2014). "There are only a few reports of STAT3 gene mutation in human cancer cells." (PMID 24662938, 2014). "However, understanding these subtleties reflects our progress in dissecting the signaling events underlying cancer pathogenesis driven by activated STAT3." (PMID 24762632, 2014). "Interestingly, a recent study revealed that S1P/S1PR1/STAT3 signaling was an important link between chronic intestinal inflammation and colitis-associated cancer." (PMID 25472725, 2014). "Muscle STAT3 activation by IL-6 is a common feature of cancer-associated muscle wasting." (PMID 24787299, 2014). "Indeed, constitutive STAT3 activation is associated with various human cancers and commonly suggests poor prognosis." (PMID 24422944, 2013). "Further analysis of these cancer-related FFLs showed that the top-ranking TF STAT3 and miRNA hsa-let-7e are key regulators implicated in human cancers, which have regulated targets significantly enriched in cellular process regulations and signaling pathways that are involved in carcinogenesis." (PMID 24205155, 2013). "Given that there are no known naturally occurring activating mutations in the STAT3 gene, aberrant activation of STAT3 in many types of cancers is primarily due to overexpression or deregulation of upstream signaling molecules such as IL-6/gp130, EGF/EGFR, JAK2, or Src." (PMID 24260381, 2013). "Aberrant activation of JAK/STAT3 signaling, in particular STAT3, participates in the initiation, development and progression of human cancers via induction of STAT3 downstream genes that encode anti-apoptotic proteins, cell cycle regulators, and angiogenic factors such as Bcl-2, CyclinD1 and VEGF." (PMID 23531921, 2013). "Thus, aberrantly high IL-6 levels cause the phosphorylation of STAT3, leading to cancer cell survival." (PMID 24098947, 2013). "Because STAT3 signaling has been implicated in therapeutic resistance to several different cancer treatments, ongoing efforts to target receptor tyrosine kinase signaling networks in NSCLC would likely be improved by combination with ruxolitinib or other JAK family inhibitors." (PMID 22319590, 2012). "Regulated by STAT3, both Mcl-1 and survivin have been implicated in cancer growth." (PMID 22280969, 2012).
cancer (continued). "Although transcription factors such as NF-κB and STAT3, are key molecules implicated in cancer-related inflammation, the current study provides several novel findings demonstrating the importance of monocytes STAT3 activation in facilitating HCC progress in human patients and in an animal model." (PMID 22136659, 2011). "JAK/STAT3 has been implicated in oncogenesis, invasiveness and metastasis of some types of cancers." (PMID 22174819, 2011). "Recently, STAT3 has been implicated as a promising target for therapeutic intervention in cancer." (PMID 21575192, 2011). "Recently, Stat3 has been implicated as a promising target for cancer therapy." (PMID 20459702, 2010). "However, a variety of cancers harbour activating point mutations in Jak2 and gp130 in-frame deletion mutations, which mediate ligand-independent activation of Stat3, are found in hepatocellular carcinomas." (PMID 20478049, 2010). "Moreover, Cox-2 dependent expression of IL-6 has been implicated in STAT3 activation and IL-6-dependent STAT3 activation has been shown to increase angiogenesis in several cancers." (PMID 19523218, 2009). "Many cancers are strongly associated with constant activation of STATs, in particular Stat3." (PMID 17598902, 2007). "Therefore, restoration of Sestrin activity or STAT3 inhibition in SESN1&2-deficient cancer cells may be a potential strategy to improve the treatment outcome for patients with cancers bearing mutations in SESN1 or SESN2 genes." (PMID 39985075, 2025). "STAT3, a member of the STATs family, was identified in 1994 and has been implicated in multiple biological processes, such as wound healing, immune response, tissue regeneration, carcinogenesis, cancer stem cell (CSC) regulation, and cell proliferation and differentiation." (PMID 40166646, 2025). "However, the mechanism underlying caspase-induced STAT3 activation during liver regeneration may be different from that in cancer cells, as little DNA damage was detected in regenerating livers." (PMID 40875771, 2025). "STAT3, in particular, has been strongly linked to the progression of multiple cancer types, including malignancies of the head and neck, lungs, stomach, liver, colon, prostate, and breast, where it facilitates cancer cell proliferation, invasion, and metastasis." (PMID 40166646, 2025). "This may explain the rarity of STAT3 GOF mutations in human cancers with mutant KRAS." (PMID 38573819, 2024). "Notably, these cancer pathways are linked to both small molecule quercetin and target Stat3." (PMID 39173044, 2024). "No studies have reported how CyD may regulate wound healing independently of cell migration and proliferation in the skin; however, in cancer cell lines, CyD inhibition was associated with increased cell proliferation and enhanced cell migration, possibly by elevated STAT3 proinflammatory signaling." (PMID 38564292, 2024). "On the contrary, JAK2 gene amplification may cause persistent activation of the JAK2/STAT3 pathway, which has been linked to survival, proliferation, angiogenesis, resistance to apoptosis, carcinogenesis, and metastasis in many types of human cancer cells." (PMID 38974233, 2024). "Moreover, the interaction between STAT3 and other cancer-causing pathways introduces intricacy to the formation of tumors, since the exchange of signals may possibly enhance the cancer-causing effects." (PMID 39353898, 2024). "Moreover, we describe that STAT3 phosphorylation state determines the expression of different subsets of target genes associated with distinct biological processes, being pS727-dependent genes the most related to cellular hallmarks of cancer." (PMID 37945711, 2023). "Additionally, similar techniques helped demonstrate that the anti-malaria drug Pyrimethamine (Pyr) selectively inhibits human DHFR in cancer cell lines, which is linked to its downstream inhibition of STAT3 signaling and underlies its promising anti-cancer activity." (PMID 36837770, 2023).
cancer (continued). "Moreover, STAT3‐positive cells are associated with favorable outcomes in some cancers." (PMID 35356799, 2022). "Therefore, inhibition of CAF-CCA interaction could be considered as a potent therapeutic approach for cancers associated with IL-6/STAT3 activation." (PMID 36091805, 2022). "In the signal transducer and activator of transcription 3 (STAT3) protein family, STAT3 is a key signaling protein that is activated by diversiform growth factors and cytokines and has gained increasing attention due to its close association with malignant tumors." (PMID 35942374, 2022). "Therefore, the relationship between Jab1/CSN5 and STAT3 associated with carcinogenesis may enhance understanding of the regulatory mechanism of Jab1/CSN5 in human cancer." (PMID 35315259, 2022). "Since STAT3 activation is sustained in efferocytic BM macrophages and considered a hallmark macrophage response to engulfing apoptotic cancer cells, it was hypothesized that STAT3 activation (phosphorylation at Tyr705) is critical in HIF-1α stabilization by efferocytosis." (PMID 36496973, 2022). "Signal transducer and activator of transcription 3 (STAT3) have critical regulatory interactions with most of these Shh‐associated oncogenes and growth factor‐mediated signaling pathways, and plays an essential role in cancer stem cell maintenance, tumorigenesis, and cancer progression." (PMID 34482626, 2022). "Moreover, activation of STAT3 is associated with advanced cancer stage and metastatic disease." (PMID 34611143, 2021). "Moreover, the expression level of p-STAT3 is linked to the prognosis of cancer, suggesting that STAT3 could be a promising target for cancer." (PMID 34059647, 2021). "Our results could be caused by the arguments underlined by Aggarwal: (a) two major inflammation pathways, transcription factors p‐NFκB and p‐STAT‐3, are stimulated by risk factors for cancer; (b) cancer malignancy occurs; and (c) in many cancer types, p‐NFκB and p‐STAT‐3 are continuously active." (PMID 33289342, 2021). "Hence, mutations in the DNA-binding domain of STAT3 may be potentially useful in determining cancer diagnosis." (PMID 33535185, 2021). "In addition, inhibited autophagy activation by CQ, leading to the blockage of autophagic flux, thereby decreased the amount of IL-6, and inhibited STAT3 expression, which caused the shift from autophagy to apoptosis and increased the sensitivity of cells to cancer therapy." (PMID 34771150, 2021). "Furthermore, STAT3 has been associated with liver carcinogenesis and cancer progression." (PMID 34577085, 2021). "The BEZ235-treated cells showed a significant inhibition of the PI3K/AKT/mTOR signaling molecules and an increase in p-STAT3Tyr705 levels, indicating that re-activation of the PI3K/AKT/mTOR pathway in PTEN-deficient cancer cells may involve inhibition of STAT3 activity." (PMID 33431808, 2021). "Note that STAT3 suppresses apoptosis, but can also promote apoptosis, which may be the cause of the difference in the induction of apoptosis by miR-124 in different cancer cell types and environments." (PMID 34072894, 2021). "STAT3 inhibition may improve cancer-associated muscle wasting." (PMID 31915140, 2020). "Cancer causes inflammation, which results in the activation of transcription factors that further increase the inflammatory response, such as nuclear factor-kB (NF-kB), signal transducer and activator of transcription 3 (STAT3), and hypoxia-inducible factor 1a (HIF1a)." (PMID 32716955, 2020).
cancer (continued). "Compelling evidence from a plethora of published research reports suggest that STAT3 is implicated in cancer cell survival and suppression of STAT3 activation could effectively inhibit cell proliferation and promote apoptosis in multiple human cancers 1,2,28,33." (PMID 32328177, 2020). "Moreover, the STAT3 signaling pathway, which may be triggered by cancer cells, has been implicated in the autophagic process." (PMID 31287013, 2019). "The potency of MH in inhibiting this critical signaling pathway in cancer cells was demonstrated by the fact that as low as 0.03% solution (w/v) of MH (equivalent to a concentration of 0.3mg/mL) was sufficient to cause a significant reduction in p-STAT3 levels." (PMID 31491838, 2019). "In eukaryotes, JAK2/STAT3 engagement is associated with significant intracellular changes, through which the expression of multiple cytokines and growth factors, cell proliferation, differentiation, and apoptosis occur, which are relevant for cancer progression and drug resistance." (PMID 32565533, 2019). "However, the downstream effectors of the IL-6/STAT3 signaling axis that underlie cancer stem cell (CSC) properties are yet unknown." (PMID 30804456, 2019). "While sudden and acute induction of the IL-6 cascade promotes muscle growth, IL-6 sustained and elevated release and STAT3 activation have been associated with muscle atrophy occurrence in several catabolic conditions, such as obesity, diabetes, and age-induced sarcopenia or cancer." (PMID 31114509, 2019). "However, the STAT3 gene is very rarely altered in human malignancies by copy number variation, point mutation or methylation and rarely by gene expression according to the Catalogue of Somatic Mutations in Cancer (COSMIC) database." (PMID 29588647, 2018). "In addition, our studies provide proof-of-concept for novel potential strategies for senescence prevention through blockade of ATM-associated DNA damage response and/or inhibition of STAT1/STAT3 signaling in effector T cells for clinical immunotherapy against cancer and chronic infections." (PMID 29339767, 2018). "Interestingly, head and neck SCC cells containing a PTPRD mutation were more susceptible to a STAT3 inhibitor, suggesting that use of this type of anti-cancer drug could be utilized for more successful treatments of head and neck SCC patients." (PMID 30208623, 2018). "Thus, there is a potential risk of toxicity in the use of STAT3 inhibitors associated with inhibiting mitochondrial function, which may be unacceptable, especially in non-cancer indications, such as inflammation and fibrosis." (PMID 30081609, 2018). "Moreover, previous studies have shown that metformin, an anti-diabetic drug, could inhibit Stat3 phosphorylation and reduce risk of development in many type of cancer." (PMID 28415725, 2017). "In addition to its intrinsic role in promoting transformation and cancer progression, active STAT3 also contributes to cancer immune evasion and has been implicated in infectious (such as H. pylori and Epstein–Barr virus) and non-infectious (such as colitis) inflammation-induced carcinogenesis." (PMID 25914882, 2015). "Thus, it is possible that the subcellular compartment of the interaction helps determine STAT3 activity, and dysregulation of this interaction could be associated with pathologic conditions such as cancer." (PMID 25605256, 2015). "Interestingly, a growing body of evidence demonstrates that miRs are closely associated with the STAT3 signaling pathway supporting the existence of regulatory feedback loops between miRs and several components of the STAT3 pathway in different cancer contexts." (PMID 26116514, 2015). "Thus, STAT3 has been implicated as a potential therapeutic target for multiple human cancer." (PMID 23818927, 2013).